IRF7 (interferon regulatory factor 7)
Diseases named in the same sentence as IRF7 in open-access papers (continued):
Sharing a sentence is not in itself a finding about the gene and the disease.
viral infection (continued). "In addition, dozens ISGs, among which some have been characterized for their antiviral activities against various other viral infections, for example Mx1, Ifit1, Isg15, Ifi44, Ddx60, Oasl and Irf7 were up-regulated upon HDV inoculation in hNTCP-Tg mice." (PMID 25902143, 2015). "Besides IRF3, IRF7 is another main regulator of TLR-mediated type I IFN response to virus infection." (PMID 24722640, 2014). "We additionally show that the constitutive IFN-α plays a critical role in the early induction of IFN genes and some IFN stimulated genes (ISGs) through the increase in expression of genes related with induction of such genes, including IRF-7 gene, before virus infection." (PMID 24587086, 2014). "There is discrepancy if IRF7 is required for the induction of IFN-β upon virus infection." (PMID 24722640, 2014). "But there is discrepancy if IRF7 is required for the induction of IFN-β upon virus infection." (PMID 24722640, 2014). "Additional experiments showed that the level of the NFκB p65 subunit was unaffected during virus infection, and the level of IRF7 was induced 6 hrs after virus infection (the IRF7 antibody cross-reacts with another protein, IRF7 is seen as a more rapidly migrating faint band)." (PMID 21677781, 2011). "Thus, IRF7 is particularly important for the continued expression of IFN-β during viral infection, and also contributes to induction of IFN-β by co-operation with IRF3." (PMID 21931555, 2011). "However, it is well-known that type I IFN as well as viral infection induces the expression of IRF-7." (PMID 20209099, 2010). "During viral infections, several viruses utilize various strategies to block IRF7 activity; these inhibition mechanisms may be based on the interaction between viral proteins and IRF7." (PMID 36537793, 2023). "Mutations affecting IRF family members IRF1, IRF3, IRF7, IRF8, or IRF9 have been described in patients presenting with inborn errors of immunity (IEI) highlighting the importance of these factors for the cellular host defense against mycobacterial and/or viral infections." (PMID 37809068, 2023). "In addition, IRF7 is subject to ubiquitination modifications during viral infection." (PMID 37251373, 2023). "We determined that decreased phosphorylation of IRF7 and TBK-1 in CD14dimCD16+ monocytes, cDC1, and cDC2 and a subsequent decrease in STING activation in older adults was associated with the impaired primary IFN induction during the early phase of simulated viral infection." (PMID 35849213, 2022). "Next, we examined whether viral infection affects IRF7 neddylation." (PMID 34506605, 2021). "In 3T3-L1 adipocytes, IRF7 mRNA was dramatically increased after culturing for 20 days, but type I interferon was hardly detected at any time point from day 2 to 20, suggesting that type I interferon- and virus infection- independent pathways may be involved." (PMID 32437400, 2020). "However, there is discrepancy if IRF7 is required for the induction of IFN-β upon virus infection." (PMID 24722640, 2014). "Therefore, we hypothesized that OASL1 could suppress IFN-I production during chronic LCMV infection by inhibiting IRF7 production and permit persistent viral infection." (PMID 23874199, 2013). "However, this protein also inhibits expression of several genes encoding proteins that induce synthesis of IFN in response to viral infection, including Rig 1 (aka Ddx58), Mda5 (aka If1h1), Irf7 and Myd88, suggesting that it also blocks the initial production of anti-viral cytokines." (PMID 22912576, 2012). "Furthermore, large scale analysis of genes regulated by IRF7 in response to viral infection have identified CD80 as a potential target of this transcription factor in an in vitro system, suggesting a link between IRF7 and expression of certain costimulatory molecules." (PMID 22815909, 2012).
viral infection (continued). "As both IRF3 and IRF7 exert their transcriptional effect by interacting with CBP/p300 and other HAT activities, these coactivators might participate to the recruitment of HDAC activities that target chromatin-associated histones during viral infection." (PMID 22685561, 2012). "Our previously published in vitro data indicated that these effects may be associated with epigenetic modification of the interferon regulatory factor 7 (IRF7) gene, leading to suppressed expression of this key transcription factor in the context of a viral infection." (PMID 20920950, 2011). "SIRT7 decreases IRF3/IRF7 phosphorylation to block the interaction between tbk1 and IRF3/IRF7, resulting in the suppression of antiviral responses, disruption of SIRT7 increases the survival rate of carp during virus infection." (PMID 40636259, 2025). "When bat IRF7 was overexpressed in bat TB 1 Lu cells, we observed significant increases in the expression of IFN-β and OAS1 both before and after VSV-GFP virus infection." (PMID 40108733, 2025). "It promotes the SUMOylation of IRF7, reducing its activity and subsequently decreasing IFN production during viral infections." (PMID 40421416, 2025). "During the activation of the cGAS-STING signaling pathway, cytoplasmic IRF7 undergoes dimerization and translocation into the nucleus, facilitating the transcription of the IFN-β gene to counteract viral infection." (PMID 40704898, 2025). "However, the role of bat IRF7 during viral infection remains unclear." (PMID 40108733, 2025). "The interferon regulatory factor 7 (IRF7), which is essential for type I IFN induction during viral infections, interacts with PEDV M to suppress type I IFN production, thereby promoting PEDV replication." (PMID 40944942, 2025). "While reconstitution of IRF7 expression restored IFN-β production upon poly(I:C) stimulation to the level of PHH and PH5CH, induction by virus infection revealed more diverse results." (PMID 40407345, 2025). "Viral infection induces the expression of canonical type I IFNs, such as IFN-β, via IRF3 and IRF7 transcription factors." (PMID 39668245, 2025). "Conversely, IRF7 has been confirmed to reconstitute corresponding IFN signaling to respond to both DNA and RNA viral infections in chicken." (PMID 39872942, 2024). "During viral infection, MyD88 is upregulated, and the interaction of MyD88 through its TIR domain with IRF-3/IRF-7 sequesters IRF-3/IRF-7." (PMID 39125989, 2024). "In response to viral infection, IKKε acts as a key molecule in the regulation of innate immunity by activating IRF3 or IRF7." (PMID 38315275, 2024). "IRF7 is known as the master regulator of type I IFN and is critical for immunity against virus infection." (PMID 38479600, 2024). "Upon virus infection, nuclear translocation of IRF3 was inhibited by the S97D substitution in IRF3 (which imitates the phosphorylated condition) in IRF3- and IRF7-knockout cells." (PMID 38396775, 2024). "The interaction of MAVS with TRAF3/6 plays a crucial role in various viral infection mechanisms by activating the IRF3, IRF7, and NF-kB pathways." (PMID 38995016, 2024). "Viral infection can be detected by pattern recognition receptors (PRRs) in host cells that trigger the activation of IRF3 and IRF7, thereby inducing the production of type I IFN and IFN-stimulated genes (ISGs)." (PMID 37833891, 2023). "Prior to viral infection and near to the ILC1 area, IRF7 was expressed concentrically in the uninfected mucosa." (PMID 37047071, 2023). "Upon viral infection, a series of cellular pathways are activated subsequently to promote the translocation of phosphorylated IRF3 or IRF7 into the nucleus and initiate the transcription of type I interferon genes by attaching to IFN-α/β promoters." (PMID 37090696, 2023). "Specifically, we measured the expression of three epithelial antiviral genes, MDA5, IRF-7, and IFN-lambda, that are highly induced by virus infection but are expressed at a low level at baseline." (PMID 36992456, 2023).
viral infection (continued). "Our previous study demonstrated that AIP suppresses type I IFN production through its IRF7 interaction and therefore Aip−/− MEFs overproduce type I IFN and are thus highly resistant to virus infection." (PMID 38043800, 2023). "The results showed that the mRNA expression of IFN-β, IRF7, MDA5, TLR3, PKR, and MX-1 was significantly decreased in the overexpression group after viral infection, compared with the control group." (PMID 36995259, 2023). "During viral infection, viral DNA and RNA activate IRF3/IRF7, which activates IFNA/IFNB gene transcription." (PMID 37264110, 2023). "Studies have identified IRF7 as the primary regulator of IFN-I-dependent responses, and IRF7 knockout increased the vulnerability of mice to viral infection." (PMID 37446070, 2023). "In concomitant with IRF7 induction, NEURL3 is upregulated by NF‐κB signaling in the late phase of viral infection." (PMID 35792897, 2022). "Upon viral infections, IκB kinase-related kinases TBK1 and IKKε activate the transcription factors such as IRF3 and IRF7, resulting in IFN-β production." (PMID 39290965, 2022). "The level of IRF7 ubiquitination was reduced in Neurl3−/− livers than that in wild type controls following viral infection, further confirming NEURL3 as the E3 ubiquitin ligase of IRF7." (PMID 35792897, 2022). "Following virus infection, TBK1 phosphorylates IRF7, resulting in IRF7 dimerization and migration to the nucleus, where it binds to the IFN-β promoter." (PMID 36366509, 2022). "Although these studies illustrate the critical role of IRF7 in human viral disease, compared to IRF3, especially in human, much less is known about how IRF7 is regulated." (PMID 35013241, 2022). "Gene module 3 comprised type I interferon–responsive genes characteristic of stimulated macrophages/monocytes reacting to an active viral infection, such as ISG15, IFIT2, and IRF7." (PMID 35039442, 2022). "In response to viral infection, MAVS, a membrane-bound protein, transmits signals from RIG-I to downstream signaling molecules via the transcription factors NF-B, IRF3, and IRF7 to create inflammatory cytokines such as IFN-beta." (PMID 36776376, 2022). "IRF7 is a known master regulator of Type I interferon- and Type III interferon-dependent immune responses to virus infection." (PMID 35098923, 2022). "Like IRF3, Interferon regulatory factor 7 (IRF7) is activated through phosphorylation and plays a pivotal role in the induction of IFN gene transcription following viral infections." (PMID 36298693, 2022). "The influence of EGb on inflammatory-associated genes expression that regulate innate immune response to viral infection and cytokine production, namely IRF-3, IRF-7, tetherin, SOCS1, SOCS3, NFKB1, p65, and MxA was also examined." (PMID 35631163, 2022). "IRF7, a crucial transcription factor to trigger innate immune responses, and Mx1, an important IFN-stimulated gene (ISG), play a pivotal role against viral infection." (PMID 35392111, 2022). "Downregulation of lincRNA‐EPS during viral infection or genetic knockout of lincRNA‐EPS facilitates PKR‐STAT1 signaling axis induced antiviral genes expression, such as Mx1, Oas2, Ifit2, and Irf7." (PMID 35312140, 2022). "We identified IRF7, a master regulator of IFN responses, as one of the primary m6A targets during virus infection." (PMID 35098923, 2022). "Using RNA-sequencing and m6A RNA immuno-precipitation (RIP)-sequencing, we identified IRF7, a master regulator of IFN responses, as a primary target of m6A during virus infection." (PMID 35098923, 2022). "IRF7 (cg17114584), a member of the interferon regulatory factor (IRF) family, can regulate the response of type I IFN to viral infection." (PMID 36212830, 2022). "IRF7 is an interferon regulatory factor, inducing the production of IFN-β and is crucial in the establishment of innate immunity in response to viral infection in chickens." (PMID 35392111, 2022).
viral infection (continued). "These inhibitors were incubated with the cells 2 h before viral infection, and then endogenous IFN-α, IFN-β, STAT1, IRF7, and OAS1 mRNA expression were examined by qRT-PCR analysis at 24 hpi." (PMID 35062253, 2021). "Collectively, the IRF7 in corneal endothelial cells not only contributed to type I IFN response, but also to the mediation of viral infection-induced MHC class I upregulation and priming of CD8 arm of acquired immunity." (PMID 34389779, 2021). "Both IRF3 and IRF7 serve as a critical role in IFN-I for combating viral infection if adequate IRF3 and IRF7 bind to the promoter sites of IFN-I genes." (PMID 34880855, 2021). "Similar to mammals, both irf3 and irf7 are responsive to viral infection in a fish monocyte/macrophage cell line (RTS11), as well as primary fish macrophages, suggesting that irf3 and irf7 have a role in the immune response of fish macrophages." (PMID 34484211, 2021). "During the early stage of viral infection, IFN-I expression is predominately driven by IRF3 and IRF7 after their activation through phosphorylation." (PMID 33690734, 2021). "We observed conservation of the IRF7 gene network in the bone marrow of PVG rats, and increased frequencies of bone marrow pDCs two days post-viral infection, supporting an active role for the bone marrow during direct environmental insults to the airway." (PMID 34367159, 2021). "Ebola Zaire virus VP35 protein increases SUMOylation of interferon regulatory factor 7 and represses type I IFN transcription, leading to the enhancement of virus infection." (PMID 34372697, 2021). "ISG15, IRF7, MX1, RSAD2, and IFIT3 have been found to play a vital role in modulating immune response against the viral infection." (PMID 34631844, 2021). "Different from IRF3 that is constitutively expressed, IRF7 expression entirely depends on type I IFN signaling and is affected by viral infection." (PMID 33554733, 2021). "Multiple transcription factors including NF-κB, IRF3, IRF7, and AP1 have been reported to promote IFN-I production upon virus infection." (PMID 34315861, 2021). "For example, upon viral infection, viral DNA or RNA is recognized by the cytosolic and endosomal sensing systems which require IRF3 and IRF7 for type I IFN induction." (PMID 34389779, 2021). "Viral infection activates the TLRs signaling pathway, then the MyD88, TRIF, Mal, and/or TRAM are recruited, subsequently activating IRF3 and IRF7 to promote the expression of IFN-β further." (PMID 35173691, 2021). "Analysis of IRF7 ∆DBD cells indicated that IRF7 played an unrecognized role in MHC class I induction, and the viral infection induced-MHC class I induction was abolished by IRF7 disruption." (PMID 34389779, 2021). "IRF-7 is constitutively expressed in pDCs, where it is critical for rapid and robust type I IFN production during viral infections." (PMID 32373120, 2020). "IRF3 is expressed constitutively, whereas IRF7 is an IFN-stimulated gene, often induced during late phases of virus infection." (PMID 32046242, 2020). "The transcription factors IRF-7 and IRF-3 are key master regulators of type I IFN production during viral infection or after activation by TLR ligands." (PMID 32373120, 2020). "In response to viral infection, among the IRF family members, particularly IRF-1, IRF-3, and IRF-7 are necessary for the production of type I IFN and also IFN-inducible genes (Bego, Mercier & Cohen, 2012)." (PMID 32566414, 2020). "As a member of IRF transcription factor family that regulates IFN expression during viral infection, IRF1 plays a very important role in regulating the expression of IFNs and ISGs, in addition to NF-κB, IRF3, and IRF7." (PMID 32983049, 2020). "Consistent with the cytokine levels, the knockdown of β-arrestin 2 significantly reduced the phosphorylation of TBK1, IRF3, IRF7, and STING and also the dimerization of IRF3 during virus infection." (PMID 33243993, 2020).
viral infection (continued). "EcTBK1 was identified as a vital inhibitor in the viral infection processes of SGIV, by triggering the IRF3- and IRF7-regulated interferon promotor ISRE and IFN activity in our previous research." (PMID 32849631, 2020). "During viral infections, IRF3 is important in the early phase of inducing the transcription of IFN-α and IFN-β, which results in the IRF7 activation." (PMID 33664729, 2020). "OASL1-knockout mice studies showed that OASL1 inhibits IRF7 translation and thereby negatively regulates IFN-I production during acute and chronic viral infections." (PMID 30939763, 2019). "IRF3 plays, together with the closely related IRF7, an important role in the IFN-I signaling cascade and the control of viral infections." (PMID 30939763, 2019). "By directly binding to STING and IRF7, Meq disrupts assembly of the STING-TBK1-IRF7 complex, thereby leading to the inhibition of IRF7 activation and IFN-β induction during viral infection." (PMID 31539404, 2019). "Upon viral infection, TLR3 recruits TRIF (TIR domain-containing adaptor inducing IFN-β) and TBK1, which phosphorylate IRF3 and IRF7." (PMID 30619109, 2018). "Specifically, during viral infections, IRF3 is important in the early phase of inducing the transcription of IFN-α and IFN-β, which then can activate IRF7." (PMID 29515574, 2018). "Mouse Oasl1 specifically suppresses IRF7 translation by binding to a double stem-loop structure in its 5’UTR, thus negatively regulates IFN during viral infection." (PMID 29973937, 2018). "Confirming our initial findings, viral infection of PVG rats increased the expression of Th1 and type I IFN target genes (MX1, ISG15, IRF7, and CXCL10)." (PMID 30150981, 2018). "During Sendai virus infection, Nmi can bind to IRF7, a master regulator for Type I IFN-dependent immune responses, and target IRF7 for proteasome-mediated degradation, leading to inhibition of Type I IFN responses induced by viral infections." (PMID 29377960, 2018). "Upon viral infection, IRF3 and IRF7 reside in the cytosol and undergoes serine phosphorylation in its C-terminal region, allowing their homo- or heterodimerization and nuclear translocation." (PMID 28915824, 2017). "During the early phase of viral infection in mammals, IFNs recognize IFNR via autocrine and paracrine pathways and induce the phosphorylation of IRF7, a key regulator of the high production of IFNs in the late stage." (PMID 27438848, 2016). "Systems biology analysis of human responses to yellow fever vaccine induced a type I interferon-mediated response comparable to the MAVS-mediated CD4+ T cell response we present, including upregulation of IRF7 and various ISG including MxB, Viperin, and ISG56." (PMID 26849062, 2016). "Irf7 is a member of the IFN regulatory factors (IRF), involved in defensive responses not only against viral infections but also against DNA-damaging chemicals." (PMID 27840820, 2016). "It has been demonstrated in mice that upon ssRNA viral infection, along with IRF3, IRF7 plays a key role in the induction and modulation of type I IFN expression." (PMID 26186542, 2015). "Upon viral infection, we observed reduced serum concentrations of IFN-α and ALT in Irf7−/−→Sod1−/− mice compared to WT→Sod1−/− mice." (PMID 26588782, 2015). "IRF7: Interferon regulatory factor 7 (IRF7) activates type IFN genes in response to DNA/RNA immune complexes and viral infections." (PMID 26106387, 2015). "Similar to IRF7, IRF3 is very important in regulating the host immune response to virus infection in mammals." (PMID 26186542, 2015). "The importance of IRF3 and IRF7 in regulating the early and late phases of IFN expression during viral infection was demonstrated through the generation of IRF3 and IRF7 knock-out mice." (PMID 25798928, 2015).